GNAS (GNAS complex locus)
Diseases named in the same sentence as GNAS in open-access papers (continued):
Sharing a sentence is not in itself a finding about the gene and the disease.
cyst (28 papers, 2014 to 2025). A sac-like closed membranous structure that may be empty or contain fluid or amorphous material. "The aim of this study was to assess the additional role of KRAS and GNAS mutation analysis with Sanger Sequencing compared to conventional cyst fluid analysis with string sign, cytology, intracystic CEA, and glucose level measurement." (PMID 41464573, 2025). "The presence of KRAS or GNAS mutations in the cyst fluid is reported to be highly specific for diagnosing mucinous PCLs." (PMID 36832238, 2023). "The molecular analysis of combined KRAS and GNAS mutations has a higher sensitivity, specificity, and diagnostic accuracy for diagnosing IPMNs and MCNs when compared to cyst fluid CEA alone." (PMID 36832238, 2023). "Specifically, the presence of KRAS and GNAS mutations in cyst fluid has enhanced sensitivity and specificity for classifying mucinous lesions when compared with CEA and cytology." (PMID 35735595, 2022). "KRAS and GNAS mutations in the cyst fluid are particularly important early mutations in IPMNs as they are not found in other common types of cysts." (PMID 33673153, 2021). "GNAS mutation was detected also in cyst fluid and duodenal and pancreatic juice samples of patients with PCN." (PMID 34884643, 2021). "Recently, mutations in KRAS and GNAS have been identified in the tissue and cyst fluid of patients with IPMN." (PMID 33005852, 2020). "Existing diagnostic modalities (CT, MRI, EUS, CEA, and CA19-9 levels; KRAS and GNAS mutations; and cyst fluid cytology) are insufficient for accurately classifying IPMN patients due to their low diagnostic accuracy." (PMID 32842508, 2020). "Detection of GNAS mutation in cfDNA can serve as a novel biomarker for cyst type classification and differentiation of intestinal subtype IPMN from the other PCNs." (PMID 33082481, 2020). "Taken together, the presence of a GNAS mutation—whether in cyst fluid, tissue, or cfDNA—provides a highly specific molecular signature for IPMN and a practical discriminator from MCN and other non-mucinous entities." (PMID 40507590, 2025). "Based on the strong evidence that the recurrent GNAS mutation is specific for IPMN26,27, recent studies investigated GNAS mutation detection in other biological specimens such as cyst fluid and duodenal and pancreatic juice samples of patients with PCNs15,28–31." (PMID 33082481, 2020). "A GNAS mutation was detected in one case with CP that was accompanied by a small cyst (5 mm); this may have been representative of an early IPMN lesion." (PMID 24897499, 2014). "EUS–fine-needle aspiration (EUS-FNA) allows cyst fluid analysis; however, CEA, glucose, and KRAS/GNAS mutations show poor value for malignancy risk." (PMID 41154400, 2025). "EUS-FNA enables the acquisition of cyst fluid for cytology, the presence of mucin, CEA, amylase, glucose, and KRAS/GNAS mutations." (PMID 41154400, 2025). "Next-generation sequencing of cyst fluid for KRAS and GNAS mutations has shown high specificity for mucinous cysts." (PMID 39766167, 2024). "This test utilises selected clinical features such as symptoms, cyst size and location, as well as cyst fluid genetic and biochemical markers, including cyst CEA levels and KRAS and GNAS mutation status." (PMID 33673153, 2021). "Histologic and cyst fluid biomarkers for high-risk IPMN, including KRAS, GNAS, and MUC1/MUC2/MUC4/MUC5A, will be used in future decision making about treatment." (PMID 33145018, 2020). "Two cyst fluid cases with molecular but not cytological evidence of a mucin-producing tumor (KRAS and/or GNAS mutations in the cyst fluid, no cells) were classified by SiMBiT as HG-dysplasia." (PMID 41142529, 2025). "Similarly, cyst fluid analysis in IPMN patients shows variable positivity rates, ranging from 26% to 82% for KRAS and 27% to 66% for GNAS mutations." (PMID 39219164, 2025).
cyst (continued). "Genetic analysis of the cyst fluid also shows mutations, like KRAS and GNAS (less commonly in MCNs." (PMID 39766167, 2024). "Furthermore, mutational analysis of driver genes, such as KRAS, GNAS, or KLF4, as well as miRNA sequencing and cyst fluid telomere fusion status seem to allow the discrimination of high-risk IPMN from low risk lesions." (PMID 36611137, 2023). "Molecular analysis of preoperative cyst fluid from the IPMN/MCN/PDAC group with 36 surgical specimens in total, showed at least one mutation in KRAS or GNAS genes in 31 (86.1%), including 16 of the 21 (76.2%) cases incorrectly classified by cytology (“NEG”: n = 9, “ND”: n = 7)." (PMID 31258847, 2019). "Conversely, in another meta-analysis the authors found that if cyst fluid mutational testing for KRAS/GNAS was negative, the probabilities that the patient has an IPMN or a mucinous cystic lesion would be approximately 2% and 8%, respectively, a finding with important practical consequences." (PMID 35892490, 2022). "The test integrated three data elements: presence of VHL mutation but absence of GNAS mutation, decreased expression of a VEGF-A protein, and a combination of factors (solid component of cyst seen on imaging, aneuploidy, and presence of mutations in certain genes)." (PMID 37887627, 2023).
intraductal papillary mucinous neoplasms (28 papers, 2014 to 2026). "Activating GNAS mutations have been identified in various gastrointestinal neoplasms, including pyloric gland adenomas, duodenal gastric‐type adenocarcinomas, pancreatic intraductal papillary mucinous neoplasms, and colorectal villous adenomas." (PMID 40964650, 2026). "Recent molecular studies confirm that activating GNAS hotspot mutations (R201C/H) are virtually restricted to intraductal papillary mucinous neoplasms." (PMID 40507590, 2025). "GNAS mutations have been previously associated with cystic pancreatic neoplasms, especially intraductal papillary mucinous neoplasms (IPMN), acting as cancer initiating drivers and being conserved between precursor lesions and transformed malignant tumors." (PMID 39618336, 2024). "The high sensitivity of KRAS/GNAS mutations in conjunction with specificity regarding IPMNs (intraductal papillary mucinous neoplasms) and mucinous PCs (pancreatic cysts) respectively is noticed during NGS strategy regarding PCF contrasting Sanger sequencing." (PMID 39605899, 2024). "Activating GNAS mutations are common in mucinous neoplasms such as intraductal papillary mucinous neoplasms (IPMNs) and low-grade appendiceal mucinous neoplasms (LAMNs), and several studies have shown that GNAS mutant CRCs often contain a mucinous component." (PMID 36790480, 2023). "GNAS mutations are found in 67% of intraductal papillary mucinous neoplasms and many associated pancreatic ductal adenocarcinomas." (PMID 35975235, 2022). "Each subtype (gastric, intestinal, pancreatobiliary or oncocytic type) of pancreatic IPMNs appears to have GNAS and/or K-ras mutations at similar frequency." (PMID 34674710, 2021). "Surprisingly, GNAS mutations, which are linked to the molecular pathogenesis of pancreatic IPMN, seem to be much less important." (PMID 31814823, 2019). "Fifteen percent of patients with MAS have activating GNAS mutations in the pancreas, resulting in intraductal papillary mucinous neoplasm (IPMN)." (PMID 30484079, 2018). "Mutations in GNAS were found in 6 PDACs, which suggested that these PDACs were associated with intraductal papillary mucinous neoplasms (IPMNs), because GNAS mutations are known to be exclusive to IPMNs among the diverse pancreatic neoplasms." (PMID 29802286, 2018). "GNAS mutation identified in this study was the hotspot mutation p.R201C that is common in low-grade appendiceal mucinous neoplasm and pancreatic intraductal papillary mucinous neoplasm." (PMID 28179590, 2017). "Indeed, activating GNAS variants are associated with various sporadic endocrine and non - endocrine tumors as intraductal papillary mucinous neoplasms, GH-secreting adenoma, pituitary toxic adenoma." (PMID 40078582, 2025). "This study demonstrates that KRAS and GNAS mutations are more prevalent in patients with resected intraductal papillary mucinous neoplasms (IPMN) compared to those under clinical surveillance." (PMID 39219164, 2025). "Notably, all GNAS-mutated IPNBs are of the intestinal subtype, similar to pancreatic IPMN." (PMID 31814823, 2019). "Alternative pathways leading to pancreatic carcinoma include intraductal papillary mucinous neoplasm (IPMN) and mucinous cystic neoplasm, with IPMN often exhibiting high frequencies of mutations in the GNAS gene." (PMID 40164585, 2025). "This pooled analysis using data from 1253, 835, and 143 pancreatic IPMN patients revealed that overall KRAS, GNAS, and RNF43 mutations were detected in 61, 56, and 23 %, respectively." (PMID 27512631, 2016). "The prevalence and clinical significances of KRAS, GNAS, and RNF43 mutations in patients with pancreatic intraductal papillary mucinous neoplasm (IPMN) remain elusive." (PMID 27512631, 2016). "Concurrent activation of the KRAS and GNAS mediated signaling pathways appears to be shared with pancreatic intraductal papillary mucinous neoplasm." (PMID 24944587, 2014).
intraductal papillary mucinous neoplasms (continued). "Approximately half of pancreatic IPMNs have GNAS mutation but none of pancreatic duct adenocarcinomas have such a mutation." (PMID 34674710, 2021). "In addition, we also observed independent intraductal papillary mucinous neoplasms with KRAS G12V and GNAS R201H mutations." (PMID 32582528, 2020).
adenoma (27 papers, 2009 to 2025). A neoplasm arising from the epithelium. "Second, both tumor volume and the Ki-67 index were significantly lower in adenomas with GNAS mutations." (PMID 39513543, 2025). "As GNAS mutations are continuously present from adenoma to adenocarcinoma, resection at the adenoma stage is desirable." (PMID 40463821, 2025). "The results of our analysis demonstrate that gastric-type SNADETs are extremely rare and frequently harbor GNAS mutations in both adenomas and adenocarcinomas." (PMID 40463821, 2025). "To date, two somatic GNAS mutations affecting Q227 and R201 codons have been identified in corticotrope adenomas via DNA exome amplification and oligonucleotide probes or sequencing, without any clinical feature of MAS." (PMID 35743266, 2022). "In rare cases, somatic variants in PRKACA and GNAS have been described in patients with cortisol and aldosterone co-secreting adenoma as well." (PMID 36105398, 2022). "Analysis comparing mutational status in adenomas according to the location of lesions revealed that GNAS (p = 0.003) was significantly mutated in rectal adenomas." (PMID 35761395, 2022). "Presence of APC, KRAS, NRAS, and GNAS mutations in HGCA well matched ‘classical adenoma-carcinoma model’." (PMID 28179590, 2017). "We accordingly extended our mutation analysis to a small panel of villous, tubulovillous, and tubular adenomas to determine the frequency of GNAS mutations in a western adenoma cohort." (PMID 24498230, 2014). "Our results indicate that GNAS mutant tumors near exclusively arise in association with villous morphology present in either the cancer or the antecedent adenoma." (PMID 24498230, 2014). "In this line, predisposing genetic factors like HNF1A germline mutation related to MODY3 diabetes and GNAS mosaic somatic mutations related to McCune Albright disease are strong risk factors of adenomas occurrence." (PMID 23401783, 2013). "Additionally, we observed a high frequency of GNAS mutations in gastric-type adenomas and APC mutations in intestinal-type adenomas, with a tendency towards mutual exclusivity." (PMID 40463821, 2025). "One macrofollicular adenoma presented a mutation in codon 201 of the GNAS gene." (PMID 19893615, 2009). "Only 12% of macrofollicular adenomas presented mutations in the TSH receptor or GNAS genes." (PMID 19893615, 2009). "However, GNAS mutations are also common in gastric foveolar metaplasia and ectopic gastric mucosa, and the most effective treatment for the specific stage of the gastric metaplasia–adenoma–carcinoma sequence remains controversial." (PMID 40463821, 2025). "Likewise, in our present study, we speculate that cAMP also plays a dual role in GNAS mutation–positive adenomas." (PMID 38827318, 2024). "Mosaicism with an activating GNAS mutation is the cause of the McCune-Albright syndrome, which is characterized by numerous endocrine abnormalities, including pseudohypoparathyroidism and/or the development of adrenal hyperplasia and/or adenomas in early in life." (PMID 36313756, 2022). "Thus GNAS mutations in adenomas arise exclusively in the context of villous morphology." (PMID 24498230, 2014). "Cortisol-producing adenomas causing either Cushing's syndrome, particularly those with PRKACA or GNAS somatic mutations associated with a more severe phenotype, or mild autonomous cortisol secretion (MACS) are more commonly observed in women." (PMID 40296186, 2025). "Most cortisol-producing adenomas with overt Cushing’s syndrome are associated with mutations in the cAMP/PKA pathway (PRKACA and GNAS), which are less frequency detected in patients with PACS or ACS." (PMID 37223045, 2023). "The Brunner–Munzel test was used to quantitatively compare protein expression levels between NFPAs/non-functioning PitNETs and GH-producing adenomas and between GNAS-WT and GNAS-MT GH-producing adenomas." (PMID 36435867, 2022).
adenoma (continued). "A total of 7300 differentially expressed molecules were identified between NFPAs/non-functioning PitNETs and GHomas/somatotroph PitNETs, and 714 differentially expressed molecules were identified between GNAS-WT and GNAS-MT GH-producing adenomas." (PMID 36435867, 2022). "For example, a recent study analyzed gene expressions in cortisol-producing adenomas (CPA) with PRKACA mutation and compared to GNAS and CTNNB1 mutant CPAs." (PMID 36105398, 2022). "The presence of mutations in the GNAS gene is frequent in CRC and has been reported in advanced adenomas." (PMID 35761395, 2022). "It is interesting to note that while all GNAS mutant cancers were right-sided, GNAS mutant adenomas were found throughout the colon." (PMID 24498230, 2014). "In adenoma, we described a crosstalk between cyclic Amp and JAK/STAT pathway that explained the mild inflammatory phenotype in GNAS-mutated HCA." (PMID 23401783, 2013). "Conversely, no concomitant CTNNB1, PRKACA, PRKAR1A or GNAS somatic variant (classically met in cortisol-producing adenomas) with a germline ARMC5 alteration has been yet reported to our knowledge." (PMID 39910635, 2025). "All gastric-type adenocarcinomas had GNAS mutations as well as adenomas, while APC mutations were absent in intestinal-type adenocarcinomas and present in most adenomas." (PMID 40463821, 2025). "In one study including two foveolar adenomas of the duodenum, both harbored GNAS mutations, while no APC, KRAS, or CTNNB1 mutations were found." (PMID 33922305, 2021). "Gains in the chromosome 20 arm containing GNAS are frequently observed in pituitary brain tumours (adenomas) and may exert a mitogenic influence on the WNT signalling pathway via cAMP activation, which may provide a proliferative advantage for resistance." (PMID 32082376, 2019). "Additionally, 99% of adenomas bearing mutations in cAMP/PKA pathway-related genes (PRKACA, GNAS, or PRKAR1A) displayed high StAR expression." (PMID 27606678, 2016). "Our HGCA mutation list includes not only those in this classical model (APC and KRAS) but also those already known as adenoma genes (NRAS and GNAS)." (PMID 28179590, 2017). "Worthy of note, GNAS molecular alterations have not been reported in intestinal-type adenomas of the duodenum." (PMID 33922305, 2021). "Interestingly, GNAS mutation-positive adenomas have relatively low CNV levels, whereas GNAS mutation-negative adenomas have a high degree of genomic disruption." (PMID 33574795, 2020). "None of the microfollicular adenomas showed TSHR and GNAS mutations in the four exons explored." (PMID 19893615, 2009).
Albright hereditary osteodystrophy (27 papers, 2007 to 2026). "Mutations in GNAS can result in developmental delay, short stature, and skeletal abnormalities associated with Albright’s hereditary osteodystrophy." (PMID 37935955, 2023). "Albright’s hereditary osteodystrophy (AHO) is an inherited disorder which is caused by an inactivating variant in the GNAS gene." (PMID 35871092, 2022). "PHP-Ia is caused by maternal heterozygous GNAS mutations and characterized by multiple hormonal resistance and characteristic features of Albright’s hereditary osteodystrophy (AHO)." (PMID 34740356, 2021). "Loss-of-function and gain-of-function mutations within Gsα-coding GNAS exons are found in various human disorders, including Albright’s hereditary osteodystrophy, pseudohypoparathyroidism, fibrous dysplasia of bone, and some tumors of different origin." (PMID 19412439, 2007). "Albright hereditary osteodystrophy (AHO) is caused by heterozygous inactivating mutations in GNAS." (PMID 36662765, 2023). "Inactivating mutations in exons 1–13 of the GNAS gene can result in the expression of a defective Gsα protein, which can cause Albright’s hereditary osteodystrophy (AHO) that presents as tissue resistance to several hormones and distinct skeletal and developmental defects." (PMID 35296306, 2022). "The stop-gain variant in GNAS is present in the highly variable first exon of the gene and is likely to result in nonsense-mediated RNA decay; in contrast, pathogenic GNAS variants that cause Albright hereditary osteodystrophy (MIM: 103580) are located in later, highly constrained exons." (PMID 30665703, 2019). "Heterozygous loss-of-function mutations in GNAS lead to Albright hereditary osteodystrophy (AHO), which is characterized by short stature, brachydactyly, developmental delay or mental deficits, and facial defects such as orbital hypertelorism and depressed nasal bridge." (PMID 26859889, 2016). "Monoallelic disease-causing variants were identified in FBN1 (acromicric dysplasia, n = 3) and GNAS (Albright hereditary osteodystrophy (AHO), n = 1)." (PMID 42151490, 2026). "Maternally inherited inactivating GNAS mutations are the most common cause of parathyroid hormone (PTH) resistance and Albright hereditary osteodystrophy (AHO) leading to pseudohypoparathyroidism type Ia (PHPIa) due to Gsα deficiency." (PMID 25802881, 2015). "Albright’s hereditary osteodystrophy (AHO) is an autosomal dominant syndrome characterized by obesity, short stature, round face, brachydactyly, heterotopic ossifications, and cognitive impairment, caused by loss-of-function pathogenic variants in GNAS gene." (PMID 35871092, 2022). "It is striking that these patients have not been described to have features reminiscent of paternal GNAS loss of function mutations, although the loss of the paternal GNAS allele (on chromosome 20) is associated with pre- and postnatal growth defect and Albright hereditary osteodystrophy." (PMID 26583054, 2015).